CST3 (cystatin C)
Diseases named in the same sentence as CST3 in open-access papers (continued):
Sharing a sentence is not in itself a finding about the gene and the disease.
diabetes (continued). "Some studies have also indicated that cystatin C may participate in insulin resistance and diabetes-related pathological processes through oxidative stress and inflammation." (PMID 37056689, 2023). "We observed cystatin C level was associated with severe plaque burden without significant interaction effect with sex, and diabetes." (PMID 37817071, 2023). "While the connection between Cystatin-C and diabetes may be through early kidney disease detection, there may be other possible pathways." (PMID 36094936, 2022). "Our results suggest Cystatin-C is equally predictive of diabetes in Whites, Blacks, and Latinos after controlling for relevant covariates, and thus could be an important tool for healthcare providers to use across patient populations." (PMID 36094936, 2022). "Determination of cystatin C level seems promising to assess the functional status of the kidneys and the rate of progression of kidney tissue damage in various kidney pathologies (kidney disease, diabetes, hypertension, kidney transplantation)." (PMID 35928354, 2022). "Blacks had higher rates of diabetes, mortality and higher Cystatin-C compared to Whites." (PMID 36094936, 2022). "Moreover, the independent association between a low cystatin C level and high risk of RKFD was consistent across subgroups of age, sex, CVD, hypertension, diabetes, metabolic syndrome, and gout, and these results remained robust in the sensitivity analyses." (PMID 36359307, 2022). "However, cystatin C measurement is expensive, and a recent study reported that it is affected by various chronic inflammatory conditions associated with diabetes mellitus (DM), obesity, and smoking." (PMID 35308546, 2022). "A recent study showed that cystatin C (CysC) was independently associated with PAD in type 2 diabetes mellitus patients without overt nephropathy, while 24 h-urine albumin and serum creatine were not independent risk factors for PAD." (PMID 35392484, 2022). "Soluble E selectin was higher in diabetic cardiovascular disease than in diabetes alone (p = 0.045), whilst cystatin-C (p = 0.004) and soluble P selectin (p < 0.001) were higher in diabetes and diabetic cardiovascular disease than in cardiovascular disease alone." (PMID 35996503, 2022). "However, in the SEARCH for Diabetes in Youth study, higher levels of cystatin C were found in healthy subjects compared to type 1 and type 2 diabetes patients." (PMID 35208542, 2022). "In patients with diabetes, further negative associations of the FA were found with cystatin C (r = −0.45; p < 0.001)." (PMID 33746707, 2021). "In addition, serum cystatin C was positively correlated with age and duration of diabetes, as seen in previous studies." (PMID 33996155, 2021). "In order to reduce the potential impact of hypertension and diabetes on this study, we conducted a subgroup analysis of serum cystatin C and eGFR based on whether the study included patients with hypertension and diabetes." (PMID 32440991, 2021). "We considered, separately for men and women, potential mediating effects of the following variables: CRP, creatinine, vitamin D, calcium, ALP, IGF1, SHBG, testosterone, testosterone/SHBG, estradiol, phosphate, cystatin C, hypertension, diabetes, and hypercholesterolemia." (PMID 32964541, 2021). "In addition, uric acid, urea nitrogen, creatinine and cystatin C were increased and eGFR was decreased in COVID-19 patients with diabetes." (PMID 33557785, 2021). "Penalised regression models selected income, cardiovascular disease, hypertension, diabetes, cystatin C, and oral steroid use as jointly contributing to COVID-19 mortality risk; Black ethnicity, hypertension and oral steroid use contributed to COVID-19 but not non-COVID-19 mortality." (PMID 33587202, 2021). "Cystatin-C is a biomarker of kidney function, which may be altered at the preclinical and clinical stages of diabetes." (PMID 34083497, 2021).
diabetes (continued). "Variable selection models consistently selected (≥ 96% selection proportion) age, male sex, Black ethnicity as well as earning less than GBP 18,000 per year, cystatin C, cardiovascular disease, hypertension, diabetes, and history of oral steroid use as jointly contributing to risk of COVID-19 death." (PMID 33587202, 2021). "Penalised regression selected (selection proportion ≥ 96%) age, male sex, renting, earning less than 18,000 GBP, current smoking, cholesterol, cystatin C, history of taking ACEi, cancer, diabetes, and cardiovascular and respiratory disease as jointly contributing to non-COVID-19 mortality." (PMID 33587202, 2021). "Serum cystatin C and the Gensini score were significantly elevated in diabetes patients." (PMID 32306911, 2020). "To date, the relationship between cystatin C and multivessel disease in diabetes mellitus patients remains unclear." (PMID 32306911, 2020). "Serum cystatin C is significantly correlated with the presence of multivessel disease, suggesting that cystatin C might be utilized as a screening tool for predicting multivessel disease in type 2 diabetes mellitus patients with normal renal function." (PMID 32306911, 2020). "In addition, a systematic review including 23 studies came to the conclusion that cystatin C-based eGFR represents measured GFR well in patients with diabetes." (PMID 33161898, 2020). "Therefore, cystatin C was a useful biomarker for the identification of multivessel disease in subjects with diabetes mellitus." (PMID 32306911, 2020). "However, the performance of various equations in CKD cohorts remains controversial due to serum creatinine is influenced by age, muscle mass, sex, and race; cystatin C level is affected by ages, body mass index, diabetes, and inflammation." (PMID 31636737, 2019). "In fact, high cystatin-C predicts the appearance of diabetes." (PMID 31561432, 2019). "Recent studies also indicated that the relationship between cystatin C and diabetes was dependent of central adiposity, and cystatin C was significantly associated with IR independent of filtration rate." (PMID 31317040, 2019). "Moreover, the add on of cystatin C to traditional risk factors provided a relative high diagnostic value with area under the curve (AUC) as 0.91, suggesting the possibility of cystatin C as biomarker for cognitive decline in diabetes." (PMID 29484146, 2018). "This was supported by a decrease in plasma cystatin C with diabetes (right)." (PMID 29123192, 2017). "Moreover, the multivariate logistic regression analysis in this study revealed that hs-CRP, renal dysfunction, diabetes mellitus, STEMI, and cystatin C were independent risk factors of CIN as well." (PMID 27547760, 2016). "A previous study of non-GFR factors associated with cystatin C concentrations found diabetes mellitus, increased C-reactive protein, increased white blood cell count, and decreased albumin concentrations to be independently predictive of increased cystatin C." (PMID 27293926, 2016). "Similarly, compared with the highest quartile, participants in the lowest quartile for LDL-C were more likely to be male and White; also experiencing disproportionate CAD, diabetes, hypertension, stroke, statin use, elevated cystatin C/ACR, and reduced eGFR." (PMID 28010729, 2016). "However, it was suggested that, in persons with diabetes, cystatin C-based estimate use would result in a higher prevalence of reduced renal function than would estimate based on serum creatinine." (PMID 26347889, 2015). "The diagnostic value of cystatin C levels for detecting poor coronary collateralization persisted regardless of age, gender, presence or absence of diabetes, hypertension or renal dysfunction." (PMID 26402227, 2015).
diabetes (continued). "The generation of cystatin C is thought to be less variable than creatinine in and among individuals, but there is evidence that factors other than the GFR, like smoking, body mass index, inflammation, corticosteroid use, proteinuria, diabetes and race, have an influence on the cystatin C level." (PMID 24517214, 2014). "The aims of the present study were to evaluate the roles of serum cystatin C (SCysC) and urinary cystatin C (UCysC) in renal function impairment and investigate the optimum cut-off point for renal function impairment among patients with type 2 diabetes mellitus (DM)." (PMID 25120619, 2014). "This is the largest study of a population-based cohort of Asian Indians comparing GFR estimation using a variety of equations incorporating serum creatinine alone, serum cystatin C alone, or in various combinations with other variables (age, sex, diabetes, and weight)." (PMID 24868463, 2014). "In order to assess whether PCT is independently related to mortality risk we conducted a Cox regression analysis further adjusted for BMI, smoking, hypertension, LDL, HDL, TG, diabetes mellitus and cystatin C." (PMID 23937962, 2013). "Additionally, in this form of diabetes, the cystatin C-based GFR estimate is higher than the creatinine-based one." (PMID 22350134, 2013). "Others have argued that the strong association of cystatin C with all cause and cardiovascular mortality may be due to its association with factors other than GFR such as measures of body size, diabetes and inflammation." (PMID 22799523, 2012). "Increased sEPCR levels were found to be associated with several cardiovascular risk factors including gender (p=0.006), soluble Tissue Factor levels (p=0.0001), diabetes (p=0.0005), and factors reflecting impaired renal function such as creatinine and cystatin C (p<0.0001)." (PMID 23136988, 2012). "On univariate analyses, in diabetes kallistatin concentrations correlated significantly with cystatin C, r = 0.28; p = 0.004, calculated GFR, r = -0.25; p = 0.009, urinary albumin/creatinine ratio, r = 0.34; p = 0.001, serum creatinine, r = 0.23; p = 0.01 and serum urea, r = 0.33, p = 0.001." (PMID 20860825, 2010). "In a diabetes-driven kidney disease model, Glp1r–/– mice with streptozotocin-induced diabetes exhibited spontaneous kidney dysfunction and accelerated kidney damage as evidenced by their higher albumin-to-creatinine ratios, increased fibronectin levels, and lower cystatin C levels in the urine." (PMID 41178710, 2025). "Importantly, no change in the ECW status was observed in the essential hypertension group and untreated controls, and all analyses of the haemodynamic changes were adjusted for the differences in follow-up time, in addition to adjustments for age, cystatin-C, presence of diabetes, and BMI." (PMID 38406920, 2024). "A previous study of 778 adults (aged 20 or older) investigating Cystatin C compared to creatinine based on eGFR showed that Cystatin C was found to reduce kidney function earlier, especially in patients with diabetes, indicating it could be used as an earlier marker of kidney damage." (PMID 38932813, 2024). "While the cost of measuring cystatin C may be higher than measuring creatinine, the importance for individuals with diabetes to accurately determine renal function and to classify CKD and the cardiovascular risk justifies the utilization of cystatin C with creatinine for estimating eGFR." (PMID 39125705, 2024). "By comparison, cystatin C is released at a constant rate in health and is freely filtered at the glomerulus; however, cystatin C levels may be stimulated by inflammation, steroid use and are commonly elevated in cardiometabolic disease such as diabetes and obesity." (PMID 37641551, 2023). "Additionally, crucial risk factors, such as microalbuminuria, cystatin C, and cTNI/cTNT have not been incorporated into commonly employed risk equations for evaluating cardiovascular complications in individuals with diabetes." (PMID 37775738, 2023).
diabetes (continued). "In addition, the cystatin C level rises with the longer period of diabetes and UACR." (PMID 33996155, 2021). "However, different equations, based on creatinine or cystatin C measurements, for estimating CKD seem to have different performance characteristics in high-risk and low-risk populations and subgroups such as older adults or patients with diabetes." (PMID 33161898, 2020). "Individuals with uncontrolled diabetes (fructosamine > 286 μmol/L) also had increased serum progranulin levels (71.68±16.5 ng/mL vs. 65.05±17.3 ng/mL, P = 0.004), but stratification based on cystatin C levels revealed this difference is due to kidney disease co-morbidity." (PMID 32886731, 2020). "Therefore, it may well be, that the association between maternal cystatin C values and LGA in our study may reflect underlying endotheliosis based on an undetected diabetes or hyperglycemia or other causes." (PMID 30024915, 2018). "Furthermore, glucocorticoid therapy, thyroid disease, cancer, smoking, obesity, and diabetes may all substantially affect the Cystatin C serum concentration." (PMID 28657585, 2017). "To investigate the effects of cystatin C on clinical parameters in our study subjects, we performed simple and multiple linear regression analyses for cystatin C. The serum cystatin C level showed significant correlation with age, diabetes duration, visceral fat area, EAT, IMT, PWV and CACS." (PMID 28922364, 2017). "The exclusion of subjects with hypertension or diabetes mellitus type 2 eliminated the associations between serum creatinine or the eGFR(crea) and serum Ang-2 concentrations but did not substantially affect the findings for serum cystatin C and eGFR(cys)." (PMID 27893762, 2016). "However, a causal involvement of cystatin C in the etiology of MetS or diabetes seems unlikely since genetic elevation of plasma cystatin C was not significantly related to incidence of these diseases." (PMID 27218257, 2016). "Thus the epidemiological relationship between plasma cystatin C and CAD, despite being statistically independent from CVD risk factors, is likely to be explained by correlation between cystatin C and long-term exposure to CVD risk factors such as hypertension, diabetes and impaired renal function." (PMID 26057752, 2015). "However, factors such as BMI, diabetes, and inflammation may impact cystatin C levels to some degree independently of kidney function." (PMID 26347889, 2015). "In contrast, diabetes status and logarithmized cystatin C levels associated significantly but negatively with AAA, with OR 0.437 (95% C.I.: 0.215–0.891, P = 0.023) and 0.356 (95% C.I.: 0.212–0.595, P<0.001) for diabetes and logarithmized plasma cystatin C levels, respectively." (PMID 22844527, 2012). "However, cystatin C level may be elevated in patients with diabetes, thyroid disease and in those with elevated levels of inflammatory markers as well as in those treated with steroids (15 patients in this study with median daily dose of 7.5 mg prednisolone)." (PMID 21223578, 2011). "QTVI correlated with type 1 diabetes duration and HbA1cAUC at baseline and type 1 diabetes duration, cystatin C and age were independent determinants for QTVI in children with diabetes in multivariable regression." (PMID 41219438, 2026). "At baseline in children with diabetes, QTVI was negatively correlated with type 1 diabetes duration, HbA1cAUC, and cystatin C (r=−0.447 p=0.004, r=–0.376 p=0.017, and r=–323 p=0.048, respectively)." (PMID 41219438, 2026). "In individuals with type 2 diabetes mellitus (T2DM), elevated levels of both plasma and urinary cystatin C (Cys-C) contribute to increased oxidation, which in turn accelerates the oxidation of low-density lipoprotein (LDL)." (PMID 40243674, 2025). "Predictors of incident HF remained similar with estimated glomerular filtration rate by creatinine and cystatin C (eGFRcyscr), UACR, and diabetes being independent predictors." (PMID 39895851, 2025).
diabetes (continued). "Despite these findings, the interplay between the five indices derived from cystatin C and creatinine and GDF‐15 remains poorly understood, particularly in individuals with diabetes mellitus." (PMID 40700030, 2025). "Longer duration of diabetes and other measure of renal filtration function such as creatinine clearance or Glomerular Filtration Rates (GFR) or cystatin C are of interest in future studies." (PMID 38397785, 2024). "Furthermore, the association between cystatin C and cardiovascular death may be stronger in participants aged 60 years or older, those without diabetes mellitus, and those without CVD." (PMID 39044229, 2024). "Adjustments were implemented in Model 3, which included hypertension, diabetes, chronic lung disease, CRP, HBA1c, TG, LDL-C, UA, Scr, Cystatin C, and TyG-BMI, as well as age, gender, smoking, and drinking status." (PMID 39606701, 2024). "Individuals with diabetes had significantly higher levels of Gal-4, higher prevalence of IHD, higher BMI, higher levels of GIP, triglycerides, cystatin c, and FPG, along with higher HOMA-IR, compared to individuals without diabetes." (PMID 37985679, 2023). "There is a lack of research regarding the relationship between creatinine to cystatin C to waist circumference ratio (CCR/WC ratios) and the development of type 2 diabetes mellitus (T2DM)." (PMID 37408146, 2023). "Mean age, BMI, waist and hip circumference, SBP, prevalence of men, hypertension, diabetes, dyslipidemia, stroke, smoking, creatinine, UA, BUN and Triglyceride significantly increased with serum cystatin C tertiles." (PMID 37817071, 2023). "Considering that aging, diabetes, hypertension, metabolic syndrome, and uric nephropathy are major etiologies of CKD, cystatin C appears to have important clinical implications for assessing the risk of RKFD in healthy subjects." (PMID 36359307, 2022). "In another study, cystatin C, NT pro BNP, cardiac troponin T, diabetes mellitus and NYHA FC III-IV were independent predictors of heart failure readmission and/or mortality." (PMID 35620751, 2022). "At baseline, the mean diabetes duration was 18.4 ± 8.80 years, glycated hemoglobin (Hgb) was 7.0 ± 1.05, and eGFR was 40.3 ± 9.35 ml/min per 1.73 m2 using the 2012 CKD-EPI cystatin C and sCr formulas." (PMID 35812284, 2022). "In the multivariate model, LMW-F determinants were smoking, prior cardiovascular disease (CVD), Caucasian ethnicity, eGFR, uric acid, prior microvascular disease, cystatin C, diastolic BP, HOMA2-IR, HbA1c and diabetes duration (all p ≤ 0.01)." (PMID 34548531, 2021). "Age, male sex, Black ethnicity, cardiovascular disease, hypertension, diabetes, and history of oral steroid use were also highly selected in LASSO models, as were cystatin C and income." (PMID 33587202, 2021). "The variables significantly associated with increasing IL‐18 concentration at baseline were male sex, age, diabetes, BMI > 30 kg/m2 and increasing levels of the biomarkers NT‐proBNP, cTnT‐hs, CRP‐hs, and cystatin C." (PMID 31596518, 2019). "Subjects with prevalent diabetes at baseline had higher TG and lower HDL levels, higher BMI, increased prevalence of hypertension, and worse renal function as measured by cystatin C." (PMID 30670722, 2019). "However, this may be because factors other than renal function that affect ESRD risk, including diabetes, might also affect serum cystatin C levels, rather than because cystatin C-based eGFR is more accurately measuring GFR itself." (PMID 29520581, 2018). "Administration of EGCG to diabetic mice markedly increased serum levels of both cystatin C and NGAL compared to diabetic mice which confirmed that EGCG potentiated diabetes induced kidney damage." (PMID 28098182, 2017). "This group was also more likely to have a number of chronic medical conditions and biomarker abnormalities, including CAD, diabetes, hypertension, obesity, stroke, statin use, elevated hs-CRP/cystatin-C/ACR, and reduced eGFR." (PMID 28010729, 2016).